STAT3 (signal transducer and activator of transcription 3)
Diseases named in the same sentence as STAT3 in open-access papers (continued):
Sharing a sentence is not in itself a finding about the gene and the disease.
colorectal cancer (continued). "Our cellular assays revealed that compound NSC13626 inhibits colorectal cancer cell (CRC) growth by downregulating phosphorylation of STAT3 and arresting the cell cycle in the S phase." (PMID 30564118, 2018). "Using an evolution-guided pY291-Fas proxy, RNA interference, and site-specific phospho-protein detection, we show that pY291-Fas significantly intensifies EGFR signaling in anti-EGFR-resistant colorectal cancer cells via the Yes-1/STAT3-mediated pathway." (PMID 30127519, 2018). "Mechanistically, we determined that interleukin-6 (IL-6) was the most highly expressed cytokine in the CC-MSC conditioned medium, and promoted the progression of colorectal cancer cells through IL-6/JAK2/STAT3 signaling, which activated PI3K/AKT signaling." (PMID 29348540, 2018). "Collectively, these findings suggest that ursolic acid induces apoptotic effect via upregulation of miR-4500 and inhibition of STAT3 phosphorylation in colorectal cancer cells as a potent anti-cancer agent for colorectal cancer treatment." (PMID 30597956, 2018). "Namely, the activation of the MEK/Erk pathway in colorectal cancer cells depended on the activation of STAT3." (PMID 30127519, 2018). "Overall, our findings provide evidence that usolic acid induces apoptosis in colorectal cancer cells partially via upregulation of miR-4500 and inhibition of STAT3 phosphorylation as a potent anti-cancer agent for colorectal cancer therapy." (PMID 30597956, 2018). "Here we report that the pro-survival form of Fas not only crosstalks with the EGFR but also significantly intensifies EGFR signaling in anti-EGFR-resistant colorectal cancer cells via the Yes-1/STAT3-mediated pathway." (PMID 30127519, 2018). "Our previous results demonstrated that miR-196b-5p promotes colorectal cancer stemness and chemo-resistance via activating STAT3 signaling." (PMID 30326918, 2018). "We also illustrated that the JAK2 and STAT3 activation play a significant role in the promotion of metastasis in colorectal cancer." (PMID 29348540, 2018). "Correspondingly, the expression of the pro-survival form of Fas enhanced the EGF-induced phosphorylation of STAT3, which is important for the cancer-promoting activities, such as migration of colorectal cancer cells." (PMID 30127519, 2018). "IL-6 was the most highly expressed cytokine in the human colorectal cancer-derived mesenchymal stem cells conditioned medium, and promoted the progression of colorectal cancer cells through IL-6/JAK2/STAT3 signaling, which activated PI3K/AKT signaling." (PMID 30175384, 2018). "The downregulated migration activity was revealed to be linked with the inactivation of Janus kinase/STAT3/matrix metalloproteinase 3 (JAK2/STAT3/MMP3) pathway in human colorectal cancer HCT-116 cells." (PMID 30380774, 2018). "Thus, inhibition of the NF-κβ and STAT3 factors appears to be associated with clinical benefits in IBD, where the inhibition of persistent activation of STAT3 by NF-κβ may be an alternative in explaining the pathogenesis and treatment of colorectal cancer associated with colitis." (PMID 30545135, 2018). "In this study, we employed the phosphorylated STAT3 and NFκB as an inflammation biomarker in colorectal cancer and tested resveratrol for its anti-inflammatory effects." (PMID 30250641, 2018). "Recently, a CEACAM1-associated decrease of STAT3 activity and CCL2 secretion was found in colorectal carcinoma, thus regulating inflammatory signalling networks and decreasing metastatic burden." (PMID 30050594, 2018). "an inflammatory cytokine, like interleukin-6 (IL-6), potentially triggers Fra-1 gene transcription by binding STAT3 to the promoter of Fra-1 gene in colorectal carcinoma (CRC) cells." (PMID 29914371, 2018). "Collectively, RAB3C upregulation facilitates colorectal cancer metastasis by promoting IL-6 secretion and recruiting members of the STAT3-related pathway." (PMID 28784136, 2017).
colorectal cancer (continued). "We found that using interleukin 6 to induce p-STAT3 activation in colorectal cancer cell lines can result in vasculogenic mimicry and using AG490 to suppress p-STAT3 activation restrained vasculogenic mimicry." (PMID 29333928, 2017). "In summary, our study observed that miR-375 suppressed the cell proliferation and tumor formation in colorectal cancer by mainly targeting both JAK2/STAT3 and MAPK/ERK signaling pathways." (PMID 28186962, 2017). "Clinical studies have revealed that expression of TNF-α and IL-6 and activation of NF-κB and STAT3 are increased in patients with active UC and particularly in those who progress to colorectal cancer." (PMID 28300788, 2017). "It is reported that knockdown of Stat3 significantly increased E-cadherin expression in colorectal cancer cells." (PMID 28108732, 2017). "Our present results suggest the essential role of IL-6/STAT3/miR-92a/Wnt/β-catenin pathway in regulating the stem cell-like traits of colorectal cancer cells and provide a potential target for colorectal cancer therapy." (PMID 29254202, 2017). "IL-22 binds to the receptor complex comprising IL-10R2 and IL-22R1 to activate the transcription factor STAT-3 and promote tumor progression in several cancer types, including colorectal cancer and BC." (PMID 29262587, 2017). "We have demonstrated that JAK/STAT3 signaling pathway was activated during the transition of NECs toward TECs induced by colorectal carcinoma microenvironment." (PMID 28967875, 2017). "On the whole, we demonstrate for the first time that the colorectal carcinoma microenvironment promotes angiogenesis through coercing NECs toward TECs with the activation of JAK/STAT3/IL-8 signaling pathway." (PMID 28967875, 2017). "STAT3 was overexpressed in colorectal carcinoma and their overexpression contributed to an increase in median OS by approximately 30 months." (PMID 28536310, 2017). "We found that colorectal carcinoma CM promoted tumor angiogenesis by coercing NECs toward tumor endothelial cells (TECs) with the activation of the JAK/STAT3 signaling pathway." (PMID 28967875, 2017). "Overall, these results further suggest that the combination of curcumin and EGCG inhibits colorectal carcinoma angiogenesis in vivo by blocking JAK/STAT3/IL-8-signaling pathway." (PMID 28967875, 2017). "Taken together, these observations demonstrated that STAT3 is essential for HDACIs-induced P-gp expression in colorectal cancer cells." (PMID 27409663, 2016). "The results generated from these experiments strongly suggested that PRSS8 is a tumor suppressor in colorectal cancer, which is through inhibiting Sphk1/S1P/Stat3 signaling pathways." (PMID 27050145, 2016). "We constructed a funnel plot and performed an Egger test and a Begg test to assess potential publication bias regarding p-STAT3 expression and lymph node metastasis in colorectal cancer patients." (PMID 27504822, 2016). "Pooled ORs were used to evaluate the relationship between p-STAT3 overexpression and clinicopathological parameters of colorectal cancer patients by random effects model." (PMID 27504822, 2016). "For quantitative analysis of EBI3, IL-27p28, IL-12p35, gp130, and p-STAT3 expression levels in different types of colorectal cancer tissues, the sections were next scored for immunoreactive area as detailed earlier based on the intensity of staining." (PMID 27247488, 2016). "Constitutive STAT3 activation in colorectal cancer cells is correlated with invasion, survival, and growth of colorectal cancer cells in a colorectal tumor model in mice in vivo." (PMID 26883202, 2016). "Mechanistic studies revealed that PRSS8 inhibited Sphk1/S1P/Stat3/Akt signaling pathway, in terms of inverse association between PRSS8 and Sphk1 in human colorectal cancers and in Sphk1-/− mice." (PMID 27050145, 2016).
colorectal cancer (continued). "STAT3 has been shown to induce the tumorigenesis of human colorectal cancer; therefore we assumed that IL-32θ inhibits the activity of STAT3, tumorigenesis and various properties of CSCs." (PMID 26824417, 2016). "The combined HR was 1.43 (95% CI: 1.23–1.67, P < 0.001), which suggested a positive relationship between p-STAT3 overexpression and poorer overall survival of colorectal cancer patients." (PMID 27504822, 2016). "In this study, firstly we assessed EBI3, IL-27p28, IL-12p35, gp130, and p-STAT3 expression with clinicopathological parameters of colorectal cancer (CRC) tissues; then we evaluated the antitumor T cell responses and tumor growth with a EBI3 blocking peptide." (PMID 27247488, 2016). "Enhanced expression of IL-6 and activation of STAT3 were observed in human colorectal carcinoma samples compared to normal colorectal tissue, with higher levels of IL-6/STAT3 in low grade carcinomas." (PMID 27006530, 2016). "Consistent with this, both the activation of STAT3 and expression of total STAT3 were upregulated in colorectal carcinoma and higher levels were seen in low grade carcinoma." (PMID 27006530, 2016). "By using immunohistochemistry, western blot, and ELISA, we found in this study that IL-6 is upregulated in colorectal carcinoma especially in low grade carcinoma, accompanied with enhanced STAT3 activation." (PMID 27006530, 2016). "Levels of IL-6, STAT3, and p-STAT3 were all increased in the human colorectal carcinoma samples, with a higher increase in low grade carcinoma." (PMID 27006530, 2016). "Phosphorylated Stat3 (p-Stat3) is the active form of Stat3 that can be detected in various cancers including colorectal cancer." (PMID 25706309, 2015). "Recently the central role of HSP90 in regulation of both HIF-1a and STAT-3 and a strong antiangiogenic effect of ganetespib were confirmed in colorectal cancer." (PMID 26517240, 2015). "Previous study has demonstrated the role of IL-6R/STAT3/miR-34a feedback loop in colorectal cancer invasion and metastasis, and our previous study has shown the relationship between miRNA-34a and Eag1." (PMID 26783521, 2015). "In contrast, another study showed that HIF-1α, in cooperation with heat shock protein 90, regulates STAT3 activation and expression in colorectal cancer cells." (PMID 26272737, 2015). "For instance, IL-6, a pro-inflammatory cytokine that is abundant in the tumor stroma, induces EMT in colorectal cancer cells by phosphorylating STAT3 (signal transducer and activator of transcription 3)." (PMID 26244871, 2015). "We confirmed expressions of both IL-11 and phosphorylated STAT3 in tumour tissues of colorectal cancer patients." (PMID 28781374, 2015). "Previous studies revealed an involvement of STAT3 in EMT through inhibition of E-cadherin expression in colorectal cancer." (PMID 25638155, 2015). "B7-H4 siRNA can effectively inhibit proliferation, invasion, and migration of LOVO cells by targeting CXCL12/CXCR4 and JAK2/STAT3 signaling, which can serve as a new target for colorectal carcinoma treatment." (PMID 26078947, 2015). "IL6 is a key mediator in a mouse model of microbially induced colorectal cancer, possibly through induction of cancer-related molecular pathways such as those involving STAT3." (PMID 24885802, 2014). "In this context, it is noteworthy that IL-22 produced by ILCs facilitates the growth of cancer cells through a STAT3-dependent mechanism in a bacteria-driven mouse model of colorectal cancer." (PMID 25061260, 2014). "Leptin suppresses food intake by activating STAT3 phosphorylation in the hypothalamus; our previous study shows that PTPRT dephosphorylates STAT3 in colorectal cancers." (PMID 24949727, 2014).
colorectal cancer (continued). "Wnt signalling and the signal transducer and activator of transcription 3 (STAT3) are oncogenic signalling pathways which are deregulated in colorectal cancer (CRC)." (PMID 25348333, 2014). "Taken together, this study has revealed miR-27a as a tumor suppressor and has identified SGPP1 and Smad2 as novel targets of miR-27a, linking to STAT3 for regulating cancer cell proliferation, apoptosis and migration in colorectal cancer." (PMID 25166914, 2014). "In another study, the tumor suppressor function of STAT3 was revealed in the Apc(Min/+) mouse model of colorectal cancer." (PMID 24995504, 2014). "In vitro and in situ studies show a frequent upregulation and activation of STAT3 protein in colorectal cancer (CRC) which is one of the most common carcinomas resulting in high mortality in western countries." (PMID 25126546, 2014). "In colorectal cancer, STAT3 induced cell invasion and downregulation of E-cadherin, thus promoting tumor EMT." (PMID 25405202, 2014). "STAT3 is activated in 70% of all solid and hematological tumors, and it was found activated in 72% of colorectal carcinomas but only in 18% of colorectal adenomas." (PMID 24995503, 2014). "In the present study, we report our findings on human colorectal cancer growth suppressive activities of AL, its efficacy in inhibiting constitutive STAT3 signaling in vitro, and the effects on the processes of tumor angiogenesis and growth in vivo." (PMID 23848964, 2013). "Constitutive activation of STAT3 is one of the major oncogenic pathways involved in the development of various types of malignancies including colorectal cancer (CRC); and thus becomes a promising therapeutic target." (PMID 23800091, 2013). "In conclusion, for the first time we demonstrate that Hedyotis diffusa Willd inhibits colorectal cancer growth in vivo via promoting the apoptosis of cancer cells and inhibition of proliferation, which is mediated by the suppression of the STAT3 pathway." (PMID 22754353, 2012). "Although both transcription factors can be involved in gp130 downstream signalling, it has been demonstrated that STAT3 is necessary for the growth of colorectal cancer in mice." (PMID 22619672, 2012). "In summary, this study is the first report to demonstrate that STAT3 is activated in colorectal cancer stem cells." (PMID 21694723, 2011). "Recent work with FLLL32 showed that it induced apoptosis in human melanoma, multiple myeloma, glioblastoma, pancreatic, breast, and colorectal cancer cell lines and inhibited STAT3 phosphorylation and DNA binding." (PMID 21443800, 2011). "Constitutive activation of STAT3 has been correlated to poor prognosis in both colorectal cancer and non-small cell lung cancer." (PMID 21266077, 2011). "We have demonstrated that GO-Y030 inhibits STAT3 phosphorylation, cell viability, and tumoursphere growth in colorectal cancer stem cells expressing elevated levels of STAT3 phosphorylation in vitro." (PMID 21694723, 2011). "Here we demonstrated that colorectal cancer stem cells (ALDH+/CD133+cells) expressed higher phosphorylated or activated STAT3 compared with ALDH−/CD133− cells." (PMID 21694723, 2011). "Our results indicated that ALDH+/CD133+ subpopulation of colorectal cancer stem cells expressed higher levels of STAT3 phosphorylation compared with ALDH−/CD133– subpopulations." (PMID 21694723, 2011). "Our study also demonstrated that GO-Y030 is a potent inhibiting STAT3 for cancer stem cells and is a good drug candidate to target constitutive STAT3 signalling in colorectal cancer stem cells or cancer-initiating cells." (PMID 21694723, 2011). "This provides possible molecular mechanisms of GO-Y030-mediated inhibition of STAT3 in colorectal cancer stem cells." (PMID 21694723, 2011). "To confirm the important role of STAT3 in colon cancer stem cells, we next examined the effect of GO-Y030 in colorectal cancer stem cells." (PMID 21694723, 2011).
colorectal cancer (continued). "Our findings indicate that FLLL32 exhibits potent inhibitory activity to STAT3 and has potential for targeting multiple myeloma, glioblastoma, liver cancer, and colorectal cancer cells expressing constitutive STAT3 signaling." (PMID 20712901, 2010). "Our data in this report demonstrated that, FLLL32, a novel STAT3 inhibitor, efficiently inhibited STAT3 phosphorylation, STAT3 DNA binding activity, which resulted the induction of apoptosis in human colorectal cancer cell lines." (PMID 20712901, 2010). "A novel small molecular STAT3 inhibitor, FLLL32 was specifically designed from dietary agent, curcumin to inhibit constitutive STAT3 signaling in multiple myeloma, glioblastoma, liver cancer, and colorectal cancer cells." (PMID 20712901, 2010). "IC50 values (μM) of FLLL32, curcumin, and other JAK2/STAT3 or STAT3 SH2 inhibitors in human colorectal cancer cells (C), glioblastoma cells (G), multiple myeloma (MM) and liver (L) cancer cells." (PMID 20712901, 2010). "AG490 was used to selectively block the Jak/Stat3 signaling pathway and inhibit activation of Stat3 in colorectal cancer cells." (PMID 20482858, 2010). "In spite of the widespread involvement of LIF in the STAT3 pathway found in oncological studies, other oncogenic pathways associated with LIF exist, for instance, the LIF/p‐AMPK signaling pathway in HCC, and the LIF/STAT3/ID1/ MDM2 signaling pathway in colorectal cancer." (PMID 40416597, 2025). "Furthermore, miR-155 derived from colorectal cancer Exo stimulates the activation of fibroblasts through the SOCS1/JAK2/STAT3 signaling pathway." (PMID 40486266, 2025). "Moreover, previous research has confirmed that lycorine, a major component of APE (29.81%), directly binds to STAT3 and suppresses colorectal cancer cell growth." (PMID 40278288, 2025). "Moreover, limonin can inhibit the cell activity of colorectal cancer cells, block STAT3 signal transduction, and inhibit the proliferation, migration, invasion, and colony formation of colorectal cancer cells." (PMID 39944619, 2025). "Interestingly, γδ T-cell pSTAT3 was upregulated by multiple PDOs, consistent with previous reports of elevated STAT3 signaling and pSTAT3 communication between immune cells and colorectal cancer." (PMID 40882026, 2025). "Additionally, the activation of STAT3 by nuclear PKM2 decreases the sensitivity of colorectal cancer cells to EGFR pathway tyrosine kinase inhibitors." (PMID 40057191, 2025). "Moreover, STAT3 positively regulated the transcriptional level of β-catenin in colorectal cancer (CRC) cells." (PMID 41415834, 2025). "Also, researchers have identified that circHIPK3 targets the miR‐637/STAT3 signaling axis to upregulate Bcl‐2 and Beclin1 expression, thereby inhibiting autophagy and inducing oxaliplatin resistance in colorectal cancer." (PMID 39584047, 2024). "Thus, it is evident that PDIA3 stimulates the proliferative capacity of colorectal cancer cells by masterminding the STAT3/PD-1 signaling paradigm, in tandem with refining macrophage M2 polarization and the secretion of tissue-specific proteases." (PMID 38761176, 2024). "Hmga2 also induced M2 macrophage polarization in colorectal cancer by upregulating STAT3." (PMID 39769061, 2024). "The genes regulated by STAT3 are often involved in critical processes like cell cycle progression, inhibition of apoptosis, and angiogenesis, all of which contribute to the malignancy of colorectal cancer cells." (PMID 39272816, 2024). "Signal transducer and activator of transcription 3 (STAT3) is a critical transcription activator in angiogenesis; it has been reported that the JAK2/STAT3 and mTOR/STAT3 signaling pathways promote apoptosis and inhibit proliferation and angiogenesis in colorectal cancer cells." (PMID 38257275, 2024). "Additionally, inhibiting JAK3/STAT3 in colorectal cancer cells promoted apoptosis and inhibited cell proliferation, aligning with previous results." (PMID 38579174, 2024).